PDE10A (phosphodiesterase 10A)
Diseases named in the same sentence as PDE10A in open-access papers (continued):
Sharing a sentence is not in itself a finding about the gene and the disease.
Chorea (7 papers, 2016 to 2025). Chorea (Greek for 'dance') refers to widespread arrhythmic involuntary movements of a forcible, jerky and restless fashion. "In movement disorders, mutations in the genes encoding PDE10A and G-protein α subunit (Gαolf), both critical cAMP regulators in striatal spiny projection neurons, have been linked to chorea and dystonia." (PMID 40943492, 2025). "We discuss the more recently described entities of IgLON5, which has evidence of both immunologic and degenerative pathophysiology, in addition to PDE-10A antibody-associated chorea." (PMID 35370928, 2022). "The identification of PDE10A mutations as a cause of chorea further highlights the role of PDE10A in pathogenesis of HD and motivates longitudinal studies validating PDE10A as a marker to track disease progression." (PMID 28194132, 2017). "Given that pathogenic mutations in both PDE10A and ADCY5 cause chorea (even though PDE10A and AC5 exert opposite effects on cAMP levels), one would expect that the p.Phe300Leu and p.Phe334Leu variants exert a deleterious effect on PDE enzyme activity." (PMID 27058447, 2016). "In conclusion, we have demonstrated that de novo dominant mutations in PDE10A are the cause of a unique movement disorder characterized by benign childhood-onset chorea and typical MRI abnormalities of the striatum." (PMID 27058447, 2016). "The identification of PDE10A mutations as a cause of chorea further motivates the study of cAMP signaling in MSNs and highlights the crucial role of striatal cAMP signaling in the regulation of basal ganglia circuitry." (PMID 27058447, 2016). "Half (3/7) of patients with serum PDE10A antibodies had chorea or ballismus." (PMID 35370928, 2022). "Management of PDE10A-related disorders is based on the symptomatic treatment of chorea." (PMID 29948482, 2018). "Indeed, ADCY5- and PDE10A-related disorders seem to show a static or mildly progressive course, while GNAO1-related movement disorders are characterized by progressive chorea which can become life-threatening in some patients." (PMID 29948482, 2018).
colon tumor (7 papers, 2016 to 2025). "PDE10A has also been implicated in several malignancies, including lung, breast, and colon cancers." (PMID 41179677, 2025). "Elevated expression of PDE10A has been detected in colon tumor cells compared to normal colonocytes, and siRNA-mediated knockdown of PDE10A significantly inhibited tumor cell proliferation." (PMID 41179677, 2025). "Recently, a novel non-COX inhibitory sulindac derivative, MCI-030 (aka ADT 061), was reported with high potency and selectivity to inhibit PDE10A and colon cancer growth." (PMID 36324187, 2022). "For example, in case of phosphodiesterase 10A, which has been studied as a therapeutic target for colon cancer and neurological symptoms, 12 chemicals, mainly carboline-type alkaloids, are displayed with linkages to the target." (PMID 33917905, 2021). "PDE10A promotes β catenin nuclear translocation and transcriptional activity and proliferation in colon carcinoma cells and is overexpressed in colon tumors." (PMID 32824266, 2020). "Additionally, pharmacological inhibition of PDE10A suppressed colon tumor growth by activating cGMP/PKG signaling, which in turn blocked nuclear translocation of β-catenin." (PMID 41179677, 2025). "Moreover, stable knockdown of PDE10A using lentiviral shRNA vectors impaired the anchorage-independent growth and colony formation of colon tumor cell lines such as HT-29, SW-480, and HCT-116, reinforcing the critical role of PDE10A in sustaining malignancy." (PMID 41179677, 2025). "MCI-030, a sulindac derivative recently reported as a novel PDE10A inhibitor with chemopreventive efficacy in the Apc+/min−FCCC mouse model of colon cancer, exhibited more potent anticancer activity, with IC50 values ranging from 0.53 μM to 0.56 μM in ovarian cancer cells." (PMID 36324187, 2022). "Similar findings were reported in colon cancer cell lines (HCT116, HT29), where siRNA-mediated PDE10A knockdown mimicked pharmacological inhibition, resulting in decreased cell viability, caspase-dependent apoptosis, and reduced DNA synthesis." (PMID 41179677, 2025). "Notably, these results differ from previous studies using PDE10A inhibitors in lung and colon cancers, which concluded that cGMP/PKG signaling alone was responsible for growth inhibitory activity of PDE10A inhibitors." (PMID 36324187, 2022).
ovarian carcinoma (6 papers, 2022 to 2025). A malignant neoplasm originating from the surface ovarian epithelium. "Similarly, PDE10A overexpression in ovarian cancer has been reported to be in association with worse overall survival and upregulation of oncogenic pathways (Wnt/β-catenin, RAS/MAPK)." (PMID 41179677, 2025). "Altogether, these data suggest that PDE10A might play a role in normal physiology of the ovaries and female reproduction, and that upregulation of PDE10A in the context of ovarian cancer is associated with poor disease prognosis." (PMID 36324187, 2022). "A recent study demonstrated that inhibition of PDE10A decreased cell proliferation, induced cell cycle arrest, and increased apoptosis in ovarian cancer cells." (PMID 37345113, 2023). "When stratified by PDE10A mRNA levels, PDE10AHIGH expressing ovarian cancer patients exhibited significantly worse overall survival (22 months) in comparison to those with low (44 months; p = 0.0006) or medium PDE10A expression (45 months; p = 0.0041)." (PMID 36324187, 2022). "Altogether, our results show that PDE10A inhibition blocks three major oncogenic pathways in ovarian cancer cells, namely Wnt/β-catenin, MAPK and AKT signaling." (PMID 36324187, 2022). "Colony formation, proliferation, and migration and invasion assays were also performed to study the effects of PDE10A gene KO on malignant properties of ovarian cancer cells." (PMID 36324187, 2022). "PDE10A genetic knockout in ovarian cancer cells through CRISP/Cas9 editing lead to decreased cell proliferation, colony formation, migration and invasion, and in vivo tumor growth." (PMID 36324187, 2022). "PDE10A knockout decreases tumorigenic properties of ovarian cancer cells such as migration, invasion and in vivo growth in athymic nude mice." (PMID 36324187, 2022). "Using PDE10A inhibitors and through the generation of PDE10A knockout (KO) ovarian cancer cells, we show that PDE10A inhibition decreases ovarian cancer cell growth by inducing cell cycle arrest and apoptosis." (PMID 36324187, 2022). "Namely, we show that PDE10A inhibition in ovarian cancer cells rapidly decreased levels of total and active β-catenin as well as the expression of downstream TCF/LEF regulated genes." (PMID 36324187, 2022). "PDE10A gene knockout in two ovarian cancer cell lines, SKOV3 and OV-90, confirmed the antineoplastic activity from targeting PDE10A." (PMID 36324187, 2022). "Using small molecule inhibitors, Pf-2545920 and a novel NSAID-derived PDE10A inhibitor, MCI-030, we show that PDE10A inhibition leads to decreased ovarian cancer cell growth and induces cell cycle arrest and apoptosis." (PMID 36324187, 2022). "Our results demonstrating that PKA and PKG are necessary for the apoptotic effects of PDE10A inhibition support several recent studies in ovarian cancer." (PMID 36324187, 2022). "In summary, our results show for the first time that PDE10A as a promising target for the treatment of ovarian cancer." (PMID 36324187, 2022). "We then measured PDE10A protein levels in human ovarian cancer cell lines and compared with normal ovarian surface epithelial cells." (PMID 36324187, 2022). "A comparison of PDE10A expression levels in TCGA ovarian cancer samples and the GTEx database of normal tissue revealed that PDE10A mRNA expression was significantly lower in ovarian tumors as compared to normal ovary tissue." (PMID 36324187, 2022). "Collectively, our data suggests that PDE10A modulates a variety of oncogenic molecular pathways to promote tumorigenic properties of ovarian cancer cells in vitro and in vivo." (PMID 36324187, 2022). "In ovarian cancer, while PDE10A mRNA may be downregulated, elevated protein levels in tumor tissues and cell lines (such as OVCAR8, SKOV3) indicate post-transcriptional regulation." (PMID 41179677, 2025). "Here we evaluate PDE10A as a novel therapeutic target for ovarian cancer." (PMID 36324187, 2022).
ovarian carcinoma (continued). "Thus, we investigated if PDE10A inhibition in ovarian cancer cells blocks RAS signaling by measuring downstream effectors." (PMID 36324187, 2022). "Here, we demonstrate that PDE10A serves as a novel target for the treatment of ovarian cancer." (PMID 36324187, 2022). "PDE10A DNA gain and amplification was observed in 13.7% of the TCGA ovarian cancer patients, and this subset had significantly decreased disease-free survival when compared to the remainder of patients with heterozygous/homozygous loss or unaltered PDE10A copy number (11 vs. 18 months; p = 0.0417)." (PMID 36324187, 2022). "Thus, we show an essential role of PDE10A in ovarian cancer cells to mediate multiple aspects of malignancy." (PMID 36324187, 2022). "Altogether, our findings suggest a novel role for PDE10A in ovarian tumorigenesis, which could serve as a target for the chemoprevention or treatment of ovarian cancer." (PMID 36324187, 2022). "Our results establish PDE10A as a novel oncogenic mediator in epithelial ovarian cancer." (PMID 36324187, 2022). "Hence, our in vitro data demonstrate the efficacy of PDE10A inhibitors as chemotherapeutics for ovarian cancer, warranting further exploration of their use in in vivo model systems." (PMID 36324187, 2022). "Pf-2545920, a highly selective and potent PDE10A inhibitor previously investigated in clinical trials for treatment of CNS disorders, inhibited growth of normal ovarian surface epithelial cells and various ovarian cancer cell lines with IC50 values ranging from 7.6 μM to 28.6 μM." (PMID 36324187, 2022). "Thus, we propose that upregulation of PDE10A in ovarian cancer will lead to worse patient outcomes due to increased oncogenic signaling that provides cells with growth and survival advantages as well as a tumor microenvironment favorable for cancer progression." (PMID 36324187, 2022). "One study showed that PDE10A suppresses β-catenin and Rat sarcoma (RAS) signaling in ovarian cancer." (PMID 40961924, 2025). "In contrast to GBM, epithelial ovarian cancer, CRC, and NSCLC, showed to have a higher PDE10A expression that contributes to tumor progression, therapy resistance, and reduced patient survival." (PMID 41179677, 2025). "PDE10A and PTGS2 were significantly decreased, but ITGB7 was significantly increased in ovarian cancer." (PMID 38714753, 2024). "We also demonstrate that PDE10A inhibition leads to decreased Wnt-induced β-catenin nuclear translocation, as well as decreased EGF-mediated activation of RAS/MAPK and AKT pathways in ovarian cancer cells." (PMID 36324187, 2022). "We further demonstrate that PDE10A inhibition leads to an increase in both cAMP/PKA and cGMP/PKG signaling, and the activation of these protein kinases coincides with the growth inhibitory and apoptotic activity of Pf-2545920 and MCI-030 in ovarian cancer cells." (PMID 36324187, 2022). "While other studies have demonstrated that aberrant cyclic nucleotide signaling may contribute to ovarian cancer progression, the role of PDE10A in driving ovarian cancer has not been reported." (PMID 36324187, 2022).
breast cancer (5 papers, 2019 to 2022). A primary or metastatic malignant neoplasm involving the breast. "Genes in the Wnt pathway, breast cancer and basal cell carcinoma pathways were downregulated in SKOV3 PDE10A knockout cells." (PMID 36324187, 2022). "Pathway diagrams reveal upregulation of a majority of genes in “Pathways in cancer” and “Breast cancer” for PDE10A-HIGH expressing ovarian tumors from the TCGA (with both log-fold and perturbation analyses), whereas PDE10A KO clones show downregulation of many of these genes." (PMID 36324187, 2022).
pulmonary arterial hypertension (5 papers, 2011 to 2022). Pulmonary arterial hypertension (PAH) is a group of diseases characterized by mean pulmonary artery pressure >20 mmHg and elevated pulmonary arterial resistance leading to right heart failure. "PDE10A, which was recently validated as a novel target to treat pulmonary arterial hypertension (PAH) due to its central role in progressive pulmonary vascular remodeling, was identified as a target of baricitinib." (PMID 35551258, 2022). "PDE10A was reported also to be mechanoresponsive in pulmonary arterial smooth muscle cells of a rat model for pulmonary hypertension." (PMID 32587621, 2020). "For instance, PDE10A expression appears to play an important role in pulmonary hypertension and is expressed in the vasculature within skeletal muscles." (PMID 28822101, 2017). "The present data demonstrate that PDE10A expression is prominently induced in the structurally remodeled arterial muscular layer in pulmonary hypertensive lungs, which suggests that PDE10A contributes to the pathogenesis of pulmonary vascular remodeling." (PMID 21494592, 2011). "Nevertheless, use of PDE10 inhibitors may have additional therapeutic advantages as PDE10A is involved into the pathology of cardiovascular diseases: heart failure and pulmonary arterial hypertension." (PMID 36438799, 2022).
Anxiety (4 papers, 2014 to 2025). Intense feelings of nervousness, tension, or panic often arise in response to interpersonal stresses. "Alternatively, because PDE10A can decrease the activity of both cAMP- and cGMP-dependent signaling cascades, BLA PDE10A might modulate anxiety-like behavior by reducing cGMP activity, alone or in combination with cAMP signaling." (PMID 24782725, 2014). "Therefore, in the present study we hypothesized that Pde10a expression also would be elevated during acute and/or protracted alcohol withdrawal, periods of elevated anxiety-like behavior and heightened alcohol intake potential." (PMID 24782725, 2014). "A putative behavioral function of elevated BLA PDE10A protein levels might be to modulate stress-related behaviors because both footshock and withdrawal from alcohol can result in heightened anxiety-like behavior for days or weeks after the stressful experience." (PMID 24782725, 2014). "Future investigation into the mechanisms by which PDE10A modulates BLA activity and the role of amygdala PDE10A in regulating anxiety- and alcohol-related behaviors is of interest for developing therapies to treat both alcohol use and stress-related disorders." (PMID 24782725, 2014). "Interestingly, treatment of Foxp1± mice with the PDE10A antagonist MP‐10 (PF‐2545920) immediately after birth not only corrects behavioral abnormalities, including decreased ultrasonic vocalization, hyperactivity, and anxiety but also normalizes changes in microglia morphology and synaptic pruning." (PMID 40568906, 2025).
basal ganglia disorder (4 papers, 2010 to 2025). A disease involving the basal ganglia. "The inhibition of phosphodiesterase 10A (PDE10A) is a novel approach to the treatment of basal ganglia disorders, including TS." (PMID 39056811, 2024). "The activity, selectivity, pharmacokinetics and safety of the novel PDE10A inhibitor CPL500036 that is under clinical development for treatment of basal-ganglia disorders were assessed." (PMID 36438799, 2022). "There is considerable activity throughout the pharmaceutical industry to develop PDE10A inhibitors for the treatment of basal ganglia disorders." (PMID 20976216, 2010).
bipolar disorder (4 papers, 2011 to 2021). A disorder of the brain that causes unusual shifts in mood, energy, activity levels and the ability to carry out day-to-day tasks. "PDE10A is highly expressed in the GABAergic neurons of the olfactory tubercle and the striatum, is dysregulated in an animal model of postpartum depression, and has been genetically associated with bipolar disorder, hypo- and hyperthyroidism, and blood pressure." (PMID 33219387, 2021). "An association has been established between the striatal expression of PDE10A gene and bipolar disorder patients." (PMID 28420888, 2017).
depression (4 papers, 2013 to 2023). "Phosphodiesterase 10A, a signaling protein associated with major depressive disorder, was also downregulated (-6.5-fold) in adult rats." (PMID 23847536, 2013).
diabetes (4 papers, 2011 to 2019). "Coding polymorphisms in the consensus Chr 17 area included those linked to cancer (Fndc1, Tiam2, Zdhhc14 Has1), growth and development (Igf2r, Afdn, Tiam2, T2), immunology or diabetes itself via the energetic electron transfer chain (Tiam2, Pde10A) or basal thermal metabolism." (PMID 31661517, 2019).
Dystonia (4 papers, 2021 to 2025). An abnormally increased muscular tone that causes fixed abnormal postures. "As altered PDE10A activities are linked to dystonia, reduced basal ganglia PDE10A expression may represent a key pathogenic pathway underlying human MCT8 deficiency." (PMID 37887331, 2023). "The second dystonia-related candidate that we identified in our bioinformatic assessments was Pde10a, a cAMP- and cGMP-inactivating phosphodiesterase that is specifically expressed in striatal GABAergic medium spiny neurons (MSNs) and that regulates dopamine receptor signaling." (PMID 37887331, 2023).
epilepsy (4 papers, 2017 to 2023). A brain disorder characterized by episodes of abnormally increased neuronal discharge resulting in transient episodes of sensory or motor neurological dysfunction, or psychic dysfunction. "Epilepsy can be prominent in GNB1 and GNAO1 encephalopathy, while it is anecdotical in individuals with HPCA, PDE2A, and PDE10A pathogenic variants." (PMID 36003298, 2022). "Our data suggest that PDE10A expression was upregulated in the cortex of patients with epilepsy." (PMID 28439226, 2017). "Data from our animal studies suggested that PDE10A is involved in the acute seizure model; therefore, we hypothesized that it may play a role in epilepsy patients." (PMID 28439226, 2017). "Three de novo PDE10A mutations [c.898T>C (p.Phe300Leu), c.1000T>C (p.Phe334Leu), and c.1001T>G (p.F334C)] have been associated with childhood-onset chorea (5 to 10 years of age) with normal cognitive development and no epilepsy." (PMID 36003298, 2022). "While the clinical phenotype associated with ADCY5 and GNAL is characterized by movement disorder in the absence of epilepsy, GNAO1, GNB1, PDE2A, PDE10A, and HPCA have a broader clinical phenotype, encompassing movement disorder, epilepsy, and neurodevelopmental disorders." (PMID 36003298, 2022).
lung adenocarcinoma (4 papers, 2018 to 2026). A carcinoma that arises from the lung and is characterized by the presence of malignant glandular epithelial cells. "The transcriptomic data revealed that five genes (CAMK1D, BCAS3, DNAH1, PDE10A, and C18orf63) were differentially expressed between lung adenocarcinoma patients and healthy individuals." (PMID 41868793, 2026). "PDE10A inhibition in lung adenocarcinoma also lead to decreased activation of ERK and MEK." (PMID 36324187, 2022). "Likewise, PDE10A is overexpressed in lung adenocarcinoma, and its inhibition was found to suppress growth, demonstrating a correlation between the levels of overexpression and survival." (PMID 33658076, 2021). "Compounds 1 and 3–5 exhibited promising concentration-dependent anti-proliferative effects in lung squamous cell carcinoma cells and lung adenocarcinoma cells, which correlated with co-expression of A2AR and PDE10A and increased cellular levels of cAMP." (PMID 33658076, 2021).